ZC3H10 (zinc finger CCCH-type containing 10)
Description:
Specific regulator of miRNA biogenesis. Binds, via the C3H1-type zinc finger domains, to the binding motif 5'-GCAGCGC-3' on microRNA pri-MIR143 and negatively regulates the processing to mature microRNA.
Synonyms: ZC3HDC10; FLJ14451
Tractability: No criterion of Open Targets' tractability assessment is met for any kind of drug.
Gene: Protein-coding gene on chromosome 12 (56,118,256 to 56,127,514, forward strand). Ensembl gene ENSG00000135482.
Subcellular location: Nucleus
Subcellular location (Human Protein Atlas): Vesicles
Gene Ontology:
Molecular function: miRNA binding; protein binding; RNA binding; metal ion binding
Biological process: negative regulation of miRNA processing; post-transcriptional regulation of gene expression; regulation of RNA splicing
Cellular component: nucleus
Genetic constraint (gnomAD): Loss-of-function variants: 12 observed, 24.99 expected, observed/expected ratio (o/e) 0.48, 90% interval 0.31 to 0.78. The upper end of that interval is the gene's LOEUF score, 0.78, which puts it in group 3 of 6, group 1 being the genes least tolerant of losing a copy. Missense variants: 360 observed, 593.89 expected, observed/expected ratio (o/e) 0.61, 90% interval 0.56 to 0.66. Synonymous variants: 226 observed, 225.7 expected, observed/expected ratio (o/e) 1, 90% interval 0.9 to 1.12.
Homologues: Orthologues: chimpanzee ZC3H10 (99% identical), macaque ZC3H10 (99% identical), pig ZC3H10 (98% identical), guinea pig ZC3H10 (98% identical), dog ZC3H10 (97% identical), mouse Zc3h10 (97% identical), rabbit ZC3H10 (97% identical), rat Zc3h10 (97% identical), zebrafish zc3h10 (69% identical), tropical clawed frog zc3h10 (63% identical), Caenorhabditis elegans Y53G8AR.9 (23% identical). Paralogues in human: MBNL1 (20% identical), MBNL2 (17% identical), MBNL3 (17% identical).
Diseases named in the same sentence as ZC3H10 in open-access papers:
ZC3H10 is named in the same sentence as 7 diseases in open-access papers, as found by Europe PMC text mining. Sharing a sentence is not in itself a finding about the gene and the disease. The quoted sentences say what the papers report.
breast carcinoma (2 papers, 2010 to 2018). "Another candidate gene for fat deposition, ZC3H10 (Zinc Finger CCCH-Type Containing 10), was reported to be down-regulated in breast cancer cells and is expected to have a tumor suppressor function." (PMID 29739312, 2018).
glioma (2 papers, 2024). A benign or malignant brain and spinal cord tumor that arises from glial cells (astrocytes, oligodendrocytes, ependymal cells). "HOTAIR can also repress two crucial target genes, Calcium Binding And Coiled-Coil Domain 1 (CALCOCO1) and zinc finger CCCH-type containing 10 (ZC3H10), directly involved in the modulation of sensitivity to TMZ in U251 glioma cells." (PMID 38887279, 2024). "Lastly, regulatory elements of HOTAIR gene were observed to determine temozolomide resistance in U251 glioma cells, possibly via expressional modulation of distant genes, calcium binding, and coiled-coil domain 1 (CALCOCO1) and zinc finger CCCH-type containing 10 (ZC3H10)." (PMID 38366205, 2024).
Obesity (2 papers, 2020). Accumulation of substantial excess body fat. "ZC3H10 is an activator of UCP1 and promotes brown adipocyte differentiation, and transgenic overexpression of ZC3H10 prohibits diet-induced obesity, while the expression of ERBB3 was downregulated during lipogenesis in sebocytes." (PMID 32772766, 2020). "Consequently, Zc3h10 ablation in mice impairs the thermogenic gene program, while Zc3h10 overexpression in adipose tissue enhances the thermogenic capacity and energy expenditure, protecting mice from diet-induced obesity." (PMID 33107819, 2020).
colon cancer (1 paper, 2021). "Further analysis revealed that ZC3H10, SAMD4A, and ENOX1 are closely related to anti-tumour immunity against colon cancer." (PMID 35155186, 2021).
tumour (3 papers, 2011 to 2021). "Significant correlation was observed between the polarised M2 macrophages and ENOX1, NCAM1, SAMD4A, and ZC3H10 with respect to tumour purity." (PMID 35155186, 2021). "The targeted genes, ENOX1, NCAM1, SAMD4A, and ZC3H10, are closely related to CRC tumour-infiltrating macrophages." (PMID 35155186, 2021). "Three genes are relevant to this locus: RPL41, a ribosomal protein not considered to be related to the immune system; ZC3H10, a zinc finger protein related to tumour growth; and ESYT1, a synaptotagmin-like protein of unknown function." (PMID 21779181, 2011).
ZC3H10 also shares sentences with these, for which no sentence is quoted: developmental delay (1 paper); schizophrenia (1).